CDK4 (cyclin dependent kinase 4)
Diseases named in the same sentence as CDK4 in open-access papers (continued):
Sharing a sentence is not in itself a finding about the gene and the disease.
neutropenia (continued). "Study has documented that the median time from the first dose of palbociclib to the appearance of neutropenia was 15 days, which was earlier than the occurrence of CDK4/6i‐related PAEs in the palbociclib group in our study." (PMID 39009505, 2024). "Within 2 weeks after completion of SABR, given concomitantly with CDK4/6i, 2 episodes of grade 3 neutropenia, and 1 grade 4 neutropenia were reported." (PMID 39120877, 2024). "One patient discontinued CDK4/6i treatment after three cycles due to prolonged G3 neutropenia despite dose reductions." (PMID 36765648, 2023). "Patients with any grade neutropenia in the beginning of CDK4/6i treatment: C1D1, C1D14, or C2D1 had a higher risk of CDK4/6i dose reduction (p = 0.006; p < 0.0001; p < 0.0001, respectively)." (PMID 36765648, 2023). "Neutropenia was common (79%) and more frequent during and after concurrent RT than sequential RT (86% vs. 76%); however, CDK4/6i dose reduction rates were similar." (PMID 36765648, 2023). "A total of 38% of patients had CDK4/6i dose reduction (9/24), mainly due to neutropenia, and one patient had a dose reduction due to diarrhea." (PMID 36902831, 2023). "In our study, CDK4/6i dose reductions rates were higher due to a longer follow-up, since, e.g., recurrent G3 neutropenia also requires dose reduction." (PMID 36765648, 2023). "The adverse effects of the 4 CDK4/6 inhibitors are roughly similar, and the common (occurrence frequency ≥ 10%) adverse effects include neutropenia, diarrhea, infection, leukopenia, fatigue, nausea, liver toxicity, and so on." (PMID 37800838, 2023). "CDK4/6 inhibitors target cell proliferation resulting in toxicity, mainly bone marrow suppression manifesting as neutropenia." (PMID 36765648, 2023). "Overall, the administration of CDK4/6i was well tolerated in the study cohort with uncomplicated neutropenia being the most common adverse event." (PMID 36876172, 2023). "The most common grade 3-4 hematologic toxicity during CDK4/6 inhibitor treatments is neutropenia while other hematologic toxicities (i.e., anemia and thrombocytopenia) are uncommon and of mild to moderate severity." (PMID 37954071, 2023). "The common AEs observed with CDK4/6 inhibitors plus endocrine are neutropenia, leukopenia, diarrhea, anemia, thrombocytopenia and lymphopenia." (PMID 37644396, 2023). "In fact, despite the high rates of grade 3–4 neutropenia with CDK4/6i, the rate of infections and febrile neutropenia are extremely low, because leukopenia and neutropenia are induced through cell-cycle arrest of bone marrow precursors." (PMID 37046661, 2023). "Complicating infection accompanied by febrile neutropenia is rarely seen during treatment with CDK4/6 inhibitors, and continuing palbociclib treatment is safe in patients experiencing grade 3 neutropenia." (PMID 36635767, 2023). "It is likely that abemaciclib’s superior affinity for CDK4 over CDK6 led to its possible dose-limiting toxicity of diarrhea, whereas palbociclib and ribociclib are associated with neutropenia." (PMID 37366898, 2023). "Though seropositivity and humoral response were seemingly unaffected by CDK4/6i, the difference in cellular response was thought to be due to CDK4/6i induced neutropenia via reversible bone marrow suppression by cell cycle arrest." (PMID 36428722, 2022). "In terms of adverse effects within CDK4/6 inhibitors, pooled analysis demonstrated that abemaciclib was significantly better than others regarding neutropenia of grade ≥3 (OR, 0.035; 95% CrI, 0.0058–0.15)." (PMID 36091147, 2022). "Differences have been observed in both efficacy and severity of neutropenia among the available CDK4 & 6i, generating interest in a possible mechanistic explanation." (PMID 35813283, 2022). "Among CDK4/6 inhibitors, abemaciclib was significantly better than others in ≥3 grade neutropenia (OR, 0.04; 95% CrI, 0.01–0.15)." (PMID 36091147, 2022).
neutropenia (continued). "The authors thus claim that palbociclib-induced neutropenia is a product of CDK4/6 inhibition in the bone marrow, preventing proliferation of healthy bone marrow cells." (PMID 34065376, 2021). "The aim of this retrospective study was to evaluate the real‐world benefit of first‐line combination therapy in this cohort and to correlate treatment efficacy with neutropenia, a common toxicity of CDK4/6 inhibitors." (PMID 34590788, 2021). "As a general rule, the use of single-agent AI should be considered for selected patients who are unable to take a CDK4/6 inhibitor due to poor performance status or baseline neutropenia or potentially age > 75 years." (PMID 34609096, 2021). "The most common effects of CDK4/6 inhibitors are neutropenia, leucopenia, fatigue, nausea and cardiotoxicity." (PMID 33213401, 2020). "Among the CDK4/6 inhibitors, palbociclib has a high frequency of neutropenia, whereas abemaciclib has a high frequency of diarrhea." (PMID 32043218, 2020). "It has to be noted that all the four patients that were already on treatment with CDK4/6 inhibitors for more than three months before RT start already reported G ≥ 3 neutropenia during the previous cycles." (PMID 32788596, 2020). "Rate of grade 3–4 neutropenia os high, but comparable with that measured for CDK4/6 inhibitors alone." (PMID 32788596, 2020). "Febrile neutropenia occurred in only 1.14% of patients in CDK4/6 inhibitors plus endocrine therapy group and 0.20% of patients in endocrine therapy alone group." (PMID 33193875, 2020). "The most common side effects of the three CDK4/6 inhibitors are neutropenia, leukopenia, fatigue and nausea." (PMID 31777590, 2019). "In detail, Abemaciclib has a 50% lower neutropenia rate in contrast with Palbociclib and Ribociclib according to its better selectivity to CDK4." (PMID 31777590, 2019). "A higher activity of abemaciclib against CDK4 than against CDK6 has been suggested as the reason for reduced neutropenia compared with other CDK4/6 inhibitors." (PMID 30443290, 2018). "All three CDK4/6i can induce grade three to four neutropenia." (PMID 40922517, 2025). "Additionally, in Asian populations with a relatively low proportion of individuals with a BMI > 25, the AVFI appears to be a more reliable indicator of neutropenia than BMI in patients treated with CDK4/6 and aromatase inhibitors." (PMID 39686815, 2025). "Neutropenia is a direct effect of CDK4/6 inhibition on bone marrow function and is not caused by immune senescence mechanisms." (PMID 40002156, 2025). "However, in terms of adverse events (AEs), neutropenia is a well-documented side effect of CDK4/6 inhibitors, including ribociclib." (PMID 40002156, 2025). "As a representative agent of CDK4/6 inhibitors, ribociclib demonstrates common adverse reactions including hepatotoxicity, neutropenia, thrombocytopenia, QT interval prolongation, gastrointestinal disturbances such as nausea, diarrhea, and vomiting, along with fatigue." (PMID 41438984, 2025). "Moreover, ribociclib is associated with a lower incidence of grade ≥ 3 hematologic toxicity, grade ≥ 3 neutropenia, drug interruptions, and dose reductions, suggesting a more favorable safety profile than other CDK4/6 inhibitors." (PMID 39941794, 2025). "However, neutropenia is a well-recognized, manageable side effect of CDK4/6 inhibitors and is often treated effectively with dose adjustments." (PMID 39456537, 2024). "Dalpiciclib's broader inhibitory effects, including highly selective inhibition of CDK4/6, may result in stronger neutrophil inhibition and subsequent neutropenia side effects." (PMID 38832268, 2024). "Although the incidence of AEs is higher when combining CDK4/6i with endocrine therapy than with endocrine monotherapy, common CDK4/6i-related AEs like neutropenia and leukopenia are well-managed in clinical practice, not undermining their first-line treatment status." (PMID 38212842, 2024). "A common adverse effect of CDK4/6 inhibitors is neutropenia." (PMID 39247493, 2024).
neutropenia (continued). "The primary AEs associated with CDK4/6 inhibitors include hematologic toxicities, such as neutropenia, and non-hematologic toxicities, including fatigue, nausea, and diarrhea." (PMID 39640578, 2024). "However, the adverse reactions (such as neutropenia, diarrhea, liver and kidney damage) and off-target effects of CDK4/6 inhibitors still limit the clinical benefits in patients." (PMID 37864031, 2023). "The vast majority of patients (33 out of 38) had CDK4/6i dose reduction due to neutropenia." (PMID 36765648, 2023). "Combination therapy with CDK4/6 and mTOR inhibitors could also enable the use of lower doses, thus diminishing adverse effects and toxicity in patients, as neutropenia, leukopenia, thrombocytopenia, anemia, fatigue or diarrhea." (PMID 36792625, 2023). "Although leukopenia and neutropenia are well-known adverse events of these inhibitors, previous studies indicate that CDK4/6i could have a relevant role in promoting immune checkpoint-inhibitor action." (PMID 37046661, 2023). "A consequence of these CDK4/6i effects might be the long-term reduction in different blood cell populations and the common adverse events like neutropenia and leukopenia." (PMID 38040730, 2023). "Except for neutropenia, we focused on severe adverse events (toxicity grade 3–4), toxicities that led to the suspension of radiotherapy or CDK4/6i, and toxicities leading to dose reduction or treatment discontinuation (either RT or CDK4/6i)." (PMID 36765648, 2023). "Consequently, hematologic adverse events, including neutropenia, commonly occur after CDK4/6 inhibitor administration." (PMID 36635767, 2023). "The incidence of decreased leucopenia, neutropenia, and diarrhea was 13.16%, 10.53%, and 15.79%, respectively, and above AEs were of grade 1/2, which were substantially lower than those previously reported in CDK4/6i plus endocrine therapy." (PMID 37144559, 2023). "Neutropenia and lymphopenia are common adverse events of CDK4/6 inhibitors and this could lead to decreased production of neutralizing antibodies against SARS-CoV-2 after vaccination." (PMID 36146552, 2022). "Abemaciclib has a lesser impact on neutrophils maturation in vitro than other CDK4 & 6, which is consistent with lower incidences of neutropenia observed in clinical settings and may allow for a prolonged treatment." (PMID 35813283, 2022). "Neutropenia is also a frequent TEAE associated with abemaciclib and other CDK4 and 6 inhibitors." (PMID 33392835, 2021). "Palbociclib has been reported to exert its antitumor effects by inhibiting CDK4/6, which is significant owing to evidence showing that the mechanism for neutropenia development may differ from that due to cytotoxic chemotherapy." (PMID 34358105, 2021). "In the subgroup analysis of different CDK4/6 inhibitors, the incidences of grade 3-4 neutropenia were significantly higher in patients receiving ribociclib-based regimen (RR=47.33, 95% CI=9.67-231.61), and palbociclib-based regimen (RR=68.15, 95%CI=17.09-271.83)." (PMID 33193875, 2020). "Therefore, neutropenia resulting from CDK4/6 inhibitors is reversible, and when these inhibitors are held, cell cycle progression can recommence." (PMID 32164785, 2020). "Rate of G 3–4 neutropenia was comparable with that measured for CDK4/6 inhibitors alone." (PMID 32788596, 2020). "As with most MDM2 inhibitors that have so far reached clinical trials, side effects of NVP-CGM097 include thrombocytopenia and neutropenia which would need to be considered in any clinical application in combination with drugs with overlapping toxicity profiles such as CDK4/6 inhibitors." (PMID 32787886, 2020). "Interestingly, the neutropenia initiated by CDK4/6 inhibitors is rather different from chemotherapy-induced neutropenia for its rapid reversibility." (PMID 31777590, 2019).
neutropenia (continued). "The hematologic toxicities of neutropenia, leukopenia, and anemia were among the most frequent adverse events in the ribociclib plus letrozole arm, consistent with the known on-target effect of CDK4/6 inhibitors on hematologic precursors in the bone marrow." (PMID 29164421, 2018). "Therefore, a next generation CDK4/6 inhibitor should inhibit CDK4/6-dependent tumor growth while minimizing neutropenia, thereby reducing the need for treatment holidays and decreasing the risk of inducing drug resistance." (PMID 28418845, 2017). "Thus, the neutropenia observed in the clinic with CDK4/6 inhibitors is a consequence of the on-target effect of prolonged drug exposure, which has resulted in dosing regimens that require at least a 7-day treatment holiday to allow recovery of neutrophils." (PMID 28418845, 2017). "This suggests that palbociclib-induced neutropenia may be due to accumulation of the drug resulting in persistent inhibition of CDK4/6 in the bone marrow, thus preventing the recovery of bone marrow proliferation prior to subsequent doses." (PMID 28418845, 2017). "However, neutropenia induced by CDK4/6 inhibitors usually decreases with subsequent cycles." (PMID 41458615, 2025). "Notably, neutropenia was the most common AE in all CDK4/6 inhibitors plus endocrine studies." (PMID 37644396, 2023). "However, after RT, neutropenia was more pronounced in the second CDK4/6i cycle (p = 0.03)." (PMID 36765648, 2023). "Unlike chemotherapy-induced neutropenia, CDK4/6 i-induced neutropenia is not correlated with an increased risk of developing severe infections, possibly because CDK4/6 i does not result in irreversible damage and apoptotic cell death in white blood cell precursors in the bone marrow." (PMID 36135204, 2022). "Indeed, ESMO has recommended for the management of MBC patients during the COVID-19 pandemic that, when combining CDK4/6 inhibitors with endocrine therapies, it is needed to consider risks of neutropenia, and that the patient requires close monitoring of symptoms of infection." (PMID 33608590, 2021). "Although the mitogenic activators (MEK inhibitor) and CDKs (CDK4/6 inhibitors) play important roles in cell division and regulate transcription, both of them produced the side effect of systemic toxicity or acquired resistance and reduction of neutropenia, respectively." (PMID 34066486, 2021). "Therefore, a next generation CDK4/6 inhibitor that can inhibit proliferation of CDK4/6-dependent tumors while minimizing neutropenia could reduce both the need for treatment holidays and the risk of inducing drug resistance." (PMID 28418845, 2017). "In summary, we have identified and characterized G1T38 as a novel, potent, selective and orally bioavailable small molecule inhibitor of CDK4/6 that shows significant efficacy in CDK4/6 dependent tumors by effectively inhibiting tumor growth without causing severe neutropenia." (PMID 28418845, 2017). "Among the 2218 patients included in the analysis, 70 patients (3.2 %) developed severe neutropenia, defined as an absolute neutrophil count (ANC) of less than 0.5 × 10^9/L, during the first three months of CDK4/6 inhibitor therapy." (PMID 40907238, 2025). "The PRAEGNANT study did not specify which cyclin-dependent kinase 4 and 6 inhibitor was used, but the data were similar to those of other studies, with neutropenia, leukopenia, diarrhoea, and asthenia being the most frequent adverse effects." (PMID 40075608, 2025). "Unlike chemotherapy-induced neutropenia, which stems from bone marrow suppression, CDK4/6 inhibitor-induced neutropenia is typically nonfebrile, transient, and reversible." (PMID 40907238, 2025). "Although not designed to detect differences in the incidence of neutropenia or ECG changes between CDK4/6i, commonly known differences were observed." (PMID 40315425, 2025).
neutropenia (continued). "The CDK4/6 inhibitor was well tolerated, with occasional grade 1 neutropenia, according to the CTCAE severity scale, which did not necessitate any treatment interruptions." (PMID 39860516, 2025). "Several studies have shown that reducing the dose of CDK4/6i due to toxicity, such as neutropenia, did not worsen the efficacy of the treatment, and patients with a reduced dose of CDK4/6i responded as well as patients with a full dose." (PMID 36765648, 2023). "The higher and more selective activity of abemaciclib against CDK4 than CDK6, as well as the ratio of unbound Cmax to CDK6 potency, may explain the different rates of neutropenia observed among treatments." (PMID 35813283, 2022). "Furthermore, we have demonstrated a correlation of neutropenia, an adverse event from CDK 4/6 inhibitor therapy, as a possible biomarker of clinical benefit from CDK4/6 inhibitor therapy." (PMID 34590788, 2021). "Consistent with the safety profile of other CDK4/6 inhibitors with similar potencies for CDK4 and CDK6 (palbociclib and ribociclib), the most frequent grade 3 or 4 AEs of dalpiciclib were neutropenia and leukopenia, observed in 52.5 and 35.0% of patients respectively." (PMID 33845905, 2021). "In our pooled analysis, neutropenia was the most common Grade ≥ 3 AE; interestingly, incidence of neutropenia was not increased in patients >65 years, consistent with data reported from an FDA pooled analysis of CDK4 and 6 inhibitors in older women." (PMID 33392835, 2021). "Of note, lerociclib demonstrated a superior efficacy compared to palbociclib and did not induce severe neutropenia in an estrogen receptor positive breast cancer dog animal model, which is a common side effect of CDK4/6 inhibitors." (PMID 34065376, 2021). "Our study observed that the rates of grade ≥ 3 hematologic toxicities, including anemia, neutropenia, and thrombocytopenia, did not increase in patients receiving CDK4/6 inhibitors who also underwent palliative radiotherapy compared to those who did not receive radiotherapy." (PMID 39941794, 2025). "Granulocyte colony-stimulating factor (G-CSF) is generally not required for the management of CDK4/6 inhibitor-induced neutropenia, while a rapid neutropenia recovery is obtained by dose interruption and dose modification of the CDK4/6 inhibitor without modifying the endocrine agents." (PMID 37954071, 2023). "The most common CDK4/6i toxicities of any grade observed in pivotal phase III trials were neutropenia, leukopenia, fatigue and nausea for palbociclib, neutropenia, nausea, infections, fatigue and diarrhea for ribociclib, creatinine increase, diarrhea, fatigue, and neutropenia for abemaciclib." (PMID 30631751, 2018). "The lack of serious complications from the neutropenia may be explained by the cytostatic effect of CDK4/6 inhibition on the bone marrow which, compared with cytotoxic chemotherapy, results in a relatively short period of neutropenia." (PMID 26857361, 2016). "However, the overall impact of CDK4/6 i-based therapy on peripheral blood counts in PALOMA, MONARCH, and MONALEESA trials has not been accurately discussed, and only a single case study describes a patient who developed neutropenia, thrombocytopenia, and anaemia following a palbociclib regimen." (PMID 36135204, 2022). "None of the CDK4 & 6i impacted mature circulating neutrophils in the bloodstream; however, abemaciclib treatment resulted in a lower impact on the maturation process compared to palbociclib and ribociclib, which may contribute to lower incidence of neutropenia." (PMID 35813283, 2022).